RARB (retinoic acid receptor beta)
Diseases named in the same sentence as RARB in open-access papers (continued):
Sharing a sentence is not in itself a finding about the gene and the disease.
tumor (continued). "Some identified genes, such GSTP1, RARB, and RASSF1, which were previously suggested as methylation biomarkers for PCa, showed DMRs in tumor tissues." (PMID 35053153, 2021). "Furthermore, to confirm the tumor-origin of the PDCOs we have analyzed the expression of PC-associated epigenetic biomarkers including promoter methylation of the GSTP1, RASSF1 and APC and RARb genes by employing a novel microfluidic rare-event screening protocol." (PMID 34581895, 2021). "Moreover, among the other causes responsible of the loss of RARβ expression, the existence of truncated form of RARβ specifically expressed in tumor cells, RARβ-prime (RARβ’), lacking of the N-terminal domains of beta 2 and beta 4, was also related to the ATRA resistance." (PMID 32012980, 2020). "Using this approach, we discovered a tumour suppressive relationship between the mineralocorticoid receptor (MR) and retinoic acid receptors (RAR), in particular RARβ." (PMID 33148314, 2020). "Multiple genes, such as CDKN2A, DAPK, MGMT, RARB, RASSF1A, and TERT, have been found to be methylated early in lung premalignant lesions, and the level of methylation increases with tumor progression from premalignant lesions to neoplasms." (PMID 32751497, 2020). "CART and ctree analysis identified the combination of L1RE1 and RARB as well as L1RE1 and RASSF1 as independent methylation markers with high discriminative power between tumor and benign tissue (for each combination, 91% specificity and 100% sensitivity)." (PMID 29851970, 2018). "The meta-analysis of p14, p15, p73, APC, SOCS1, MGMT, SFRP1, PRDM2, DAPK1, RARβ, IGF2 and hMLH1 genes methylation was performed between HCC tumor tissues vs adjacent tissues and HCC tumor tissues vs normal tissues." (PMID 27835605, 2016). "In previous studies, NNK was found to induce hypermethylation of multiple tumour suppressor genes like p16, DAPK, Rarβ etc. in liver and lung tumours of rat and mouse models." (PMID 23596512, 2013). "Our results suggest that RARγ is involved in the repression of RARβ and CRBP1 expression, both of which have a tumor-suppressive function." (PMID 22920668, 2012). "DLEC1 was methylated in 38.7%, MLH1 in 35.7%, RARβ in 51.7%, RASSF1A in 32.4% and BLU in 35.3% of tumours." (PMID 18594535, 2008). "Thus, it is quite significant that RARβ protein expression could be detected in the tumours." (PMID 18349838, 2008). "Down-regulation of the RARβ mechanism (as detailed above) combined with CBP and AP-1 up-regulation triggers tumor progression and proliferation." (PMID 18625040, 2008). "However, how RARβ exerts its role as a tumor suppressor is largely unknown." (PMID 18166136, 2007). "Our data demonstrates tumour-specific promoter methylation is found in a significant proportion of cases at P16, CYGB and CYCA1, while methylation of the promoters of ECAD and RARβ was also seen in surrounding normal tissues." (PMID 16449996, 2006). "In this case, the absence of RARβ changes the composition and the expression profile of the tumor stroma sustaining mesenchymal traits in the tumor cells." (PMID 38360674, 2024). "Moreover, MiR146b-5p targets both the gene expression of RARβ and CCDC6 and promotes tumor development." (PMID 35186709, 2021). "They found higher degree of methylation of MGMT, RARβ, RASSF1A, and CDH13 in tumour specimens and of SOCS-1 in peripheral blood with higher levels of IL-6, while others found less degree of methylation of USP2, TMEM49, SMAD3, DTNB, and IL-6 promoter with higher levels of IL-6." (PMID 31205673, 2019). "Based on our results L1RE1 and RARB as well as L1RE1 and RASSF1 might serve as biomarkers for less invasive investigations such as liquid-biopsies or tumor biopsies (e.g., derived by endobronchial ultrasound transbronchial needle aspiration (EBUS-TBNA))." (PMID 29851970, 2018). "In the second node, higher methylation of either RASSF1 or RARB was able to separate the remaining tumor from the benign samples (data not shown)." (PMID 29851970, 2018).
tumor (continued). "However, combinations of two methylation biomarkers, i.e. L1RE1 and RARB or L1RE1 and RASSF1, were sufficient to discriminate tumor from benign tissue with 91% specificity and 100% sensitivity using CART classification." (PMID 29851970, 2018). "The methylation statuses of P16, RASSF1A, APC, RARβ, DAPK, CDH13, and MGMT were not linked to age, gender, smoking behavior, and tumor stage and histology in NSCLC." (PMID 28404957, 2017). "Cluster analysis showed MBCs arising in BRCA2 mutation carriers were characterised by RASSF1A, WIF1, RARβ and GTSP1 methylation (p = 0.02) whereas methylation in BRCAX tumours showed no clear clustering to particular genes." (PMID 28893223, 2017). "Nuclear receptors have also been noted as having tumor suppressive functions including VDR’s protective function in colon cancer; PPARg’s activation in reducing tumorigenicity in many cancer tissue types; TR4 and RARb as tumor suppressors in prostate, and NUR77 and NOR1 as tumor suppressors in AML." (PMID 26217306, 2015). "Eleven cancer related genes were found to have methylation (defined as more than 10 % methylation) in at least some of the tumours: RASSF1A (64 %), TWIST1 (61 %), CDH13 (51 %), APC (50 %), MAL (35 %), GSTP1 (30 %), WIF1 (26 %), RARβ (19 %), BRCA1 (2 %), CDKN2A (2 %) and TP73 (2 %)." (PMID 26452468, 2015). "Early-stage (pathological tumour (pT) 1–2) and node-negative tumours had higher median percentage methylation for RARB." (PMID 25052224, 2014). "In the tumor panel, increased promoter methylation was observed in BLU, CASP8, DCR2, CDH1, RASSF1A and RASSF2, possibly providing the second hit for BLU, RARB and RASSF1A." (PMID 22984959, 2012). "RARB hypermethylation confirmed the presence of tumor cells in only 1 out of 5 recurrent cases and was absent in all cases showing negative cytology." (PMID 18702824, 2008). "Promoter methylation was significantly elevated in tumours compared to normal tissue for p16 (P=0.048), cytoglobin (P=0.002) and cyclin A1 (P=0.001) but not in RARβ (P=0.088) or E-cadherin (P=0.347)." (PMID 16449996, 2006). "Tumor biopsies and peripheral blood samples were taken the day before and after treatment to analyze by MSP and RT-PCR the genes APC, MGMT; ER, GSTP1, DAPK, RARβ, FHIT, and p16 pre- and post-treatment for DNA promoter methylation and gene expression." (PMID 16248899, 2005). "The genes APC, MGMT; ER, GSTP1, DAPK, RARβ, FHIT and p16 were evaluated pre and post-treatment for DNA promoter methylation and gene expression by MSP (Methylation-Specific PCR) and RT-PCR respectively in each of the tumor samples." (PMID 15862127, 2005). "The growth of tumour cells was also inhibited more than that of normal cells when RARβ together with RARγ, but not RARα alone, were antagonised." (PMID 15266311, 2004). "Two patients showed promoter hypermethylation in all four tumour suppressor genes and negative expression of mRNA in RARβ, MGMT and SYK." (PMID 14970867, 2004). "This fact is not surprising since RARβ has been reported to act as a tumor suppressor." (PMID 36230951, 2022). "Moreover, a small patient subgroup who expressed RARβ on tumor tissue showed a better response (66.6%) than those without RARβ expression (42%)." (PMID 33324556, 2020). "RARβ expression in CRC specimens was clearly lower than in peritumoral specimens (30.8% vs 58.8%, p < 0.001) and significantly correlated with gender (χ2 = 3.926, p = 0.048), tumor differentiation (χ2 = 5.978, p = 0.014), and tumor stage (χ2 = 6.642, p = 0.036)." (PMID 30944670, 2019). "Indeed, 4-CPA alone was found to be a potent inhibitor of tumour development and growth, but did not enhance RARβ expression compared to controls at 4-CPA blood concentrations that were achieved in vivo." (PMID 12865937, 2003). "Thus, although it is possible that plasma concentrations of 4-CPA did not accurately reflect tumour tissue levels of the compound, it is clear that its potent antitumour effects are not mediated through enhanced RARβ signalling." (PMID 12865937, 2003).
tumor (continued). "Therefore, RARβ could act as tumor suppressor even in the absence of ATRA, and RARβ loss expression gives AP-1 over-expression, which could abrogate the growth-inhibitory effects of ATRA through RARα and RARγ, resulting in retinoid resistance." (PMID 32012980, 2020). "Further, we analyzed whether the methylation status of P16, RASSF1A, APC, RARβ, DAPK, CDH13, and MGMT there were differences in the characteristics of gene methylation in different tumor stages (early stage vs. advanced stage) and tumor histotypes (SCC vs. AC)." (PMID 28404957, 2017). "The promoter hypermethylation of RARB could inhibit the gene expression when added to the methylation inhibitor and deacetylation inhibitor like 5′-aza-2′-deoxycytidine (5-aza-dC) and trichostatin A (TSA) which could recover the gene expression and inhibit tumor cells growth." (PMID 25197641, 2014). "Tumour MtI was significantly higher than that of normal tissue in the case of P16, CYGB and CYCA1 but not RARβ or ECAD (Kruskall–Wallis test of mean rank)." (PMID 16449996, 2006).
cancer (134 papers, 1999 to 2026). A tumor composed of atypical neoplastic, often pleomorphic cells that invade other tissues. "RARB methylation showed a stronger association with cancer in comparison to the other tested genes (OR = 46.87; 95% CI: 9.61–228.54; P < 0.001)." (PMID 33718129, 2021). "Among the four genes, RARB gene promoter methylation showed the strongest association to cancer when compared to other genes at the Binary Logistic Regression analysis (OR = 15.25; 95% CI: 6.06–40; P < 0.001)." (PMID 33718129, 2021). "Upregulation of RARβ within the drug-resistant cancer cells, which exhibits loss of RARβ expression, has been shown to increase the susceptibility of cells to apoptosis induced by chemotherapeutic agents." (PMID 32293355, 2020). "RARβ plays a critical role in cancer progression and is associated with several types of human cancer." (PMID 30944670, 2019). "The loss of RARB expression has been associated with a variety of cancers (predominantly of mammary and pulmonary origin), and it has been correlated with suppressed expression of epidermal growth factor receptor (EGFR)." (PMID 29467946, 2018). "Our study highlights the association between SphK2 and abnormal modulation of RXRα/RARβ in cancer cells." (PMID 28465486, 2017). "Specifically, we investigated how the vitamin A depletion induced by cigarette smoke is related to decreased expression of RARβ, a potential cancer risk factor." (PMID 26462767, 2015). "Consistent with this idea, variable levels of RAR expression deficiency, which in the case of RARβ can be due to epigenetic silencing, is commonly observed in a variety of cancers." (PMID 23990796, 2013). "The loss of RARβ might contribute to enhanced cancer stemness and the apoptosis resistance of CSCs to gefitinib in NSCLC cells." (PMID 32293355, 2020). "It is possible to hypothesize that re-expression of PI3K/Akt signaling mediates CRBP-1 loss-induced cancer progression and RARβ down-regulation in a transcription-independent mechanism of action of atRA." (PMID 32909215, 2020). "This study presents the first evidence that six-week exposure to one, two, and three packs of cigarettes per day, five days per week, depletes lung retinoic acid in rats and is associated with increasing molecular markers for cancer while depleting the tumor suppressor RARβ." (PMID 26462767, 2015). "RARβ has been suggested to play an important role in the biological functions of RA and to be associated with cellular sensitivity to retinoids in different types of cancers." (PMID 22087283, 2011). "Finally, it was reported that specific diets (tea polyphenols, soybean genistein, or plant food isothiocyanates), might inhibit the development of cancer by reducing DNA hypermethylation in critical genes associated with cancer such as p16 Ink or RARβ." (PMID 29997595, 2018). "Among them, RARβ plays a crucial role in regulating cancer cell differentiation, proliferation, and apoptosis." (PMID 40371351, 2025). "RARB (Retinoic Acid Receptor Beta) gene methylation is one of the most frequently analysed epigenetic biomarkers in various cancers (Refs 26, 27, 28, 29)." (PMID 40524349, 2025). "Community 4 members RARB, TIMP3 and CDH13 have been implicated as tumor suppressor gene targets of DNA methylation and epigenetic regulation in cancers." (PMID 39545637, 2024). "Methylated RARB has been associated with overall survival and prognosis in all stage CRC and other cancers." (PMID 39385172, 2024). "To examine this in our cancer models, we compared the expression of RARα, RARβ, RARγ, RXRα, RXRβ and RXRγ in AB1-HA tumors, which are sensitive to combination tretinoin–CY therapy, and AE17, CT26 and WEHI164 tumors, which are resistant." (PMID 38350880, 2024). "Due to the extensive inhibitory effect of ATRA on the growth of various cancer cells, LE135 is mainly used in cancer research to verify the known inhibitory effect of ATRA on the activation of RARb in cancer cells." (PMID 36681687, 2023).
cancer (continued). "When compared to genistein, biochanin A and daidzein showed less effectiveness in inhibiting DNA methyltransferase activity, reactivating the RARβ gene, and suppressing cancer cell growth." (PMID 38067304, 2023). "In human cancer cells, it has been shown that the introduction of the p21 (sdi1) gene through infection with adenovirus, which encodes a CDK inhibitor, increases RARβ mRNA and protein expression and promotes sensitivity to ATRA." (PMID 35631448, 2022). "RARB downregulation is associated with retinoid resistance and tumorigenesis, whereas induction of RARB can suppress cancer progression." (PMID 35611845, 2022). "Daidzein has been found to be less effective in inhibiting DNMT activity, reactivating RARb, and inhibiting cancer cell growth." (PMID 35327559, 2022). "Various studies have suggested that cancer cells elevate the expression levels of RARB promoter methylation and result in functional silencing." (PMID 35974300, 2022). "RARβ gene silencing reduced the tumorigenic characteristics of A549 parental cancer cells but increased the stemness characteristics of CSCs." (PMID 33995625, 2021). "On the other hand, the silencing of RARβ enhanced the expression of BIRC5 in A549 CD166+EpCAM+ and A549 CD166-EpCAM-, suggesting that depletion of RARβ promotes the cancer cell growth via activation of the anti-apoptosis gene." (PMID 33995625, 2021). "In many cancers the activity of RARβ itself is suppressed via various pathways leading up to mTOR activation." (PMID 34178631, 2021). "RARβ played a role as a regulatory gene as the silencing of this gene led to the downregulation of cancer-related genes in A549 parental cells." (PMID 33995625, 2021). "This suggests that the silencing of RARβ enhances the cancer growth in A549 CD166+EpCAM+ and A549 CD166-EpCAM- cell populations by EDN1 overexpression of the EDN1 gene which play important role in cancer metastasis." (PMID 33995625, 2021). "AKT3, KIT proto-oncogene, receptor tyrosine kinase (KIT) and retinoic acid receptor beta (RARB) were also involved in pathways in cancer." (PMID 33176720, 2020). "Previous studies have demonstrated various relationships between clinicopathological parameters and RARβ expression in different types of cancer." (PMID 30944670, 2019). "Inactivation of RARβ by promoter hypermethylation contributes significantly to tumorigenesis of a variety of cancers including NSCLC." (PMID 28008143, 2017). "Cancer cells transfected with SphK2 antagonize all-trans retinoic acid (ATRA)-induced RARβ promoter activity through acetylated RARβ degradation." (PMID 28465486, 2017). "EGCG is active against many types of cancer cells, demethylates and reactivates several genes involved in cancer like p16, RARβ, MGMT, hMLH1, and GSTP1." (PMID 26339624, 2015). "Methylation level of DAPK1, SLIT2, WIF1 and RARB genes combined distinguished cancer from normal cervical tissues and had significantly higher specificity compared to HPV detection and age alone." (PMID 25826459, 2015). "Of these receptors, the retinoic acid receptor beta (RARβ) is expressed primarily in epithelial cells and plays a central role in mediating the growth inhibition of different types of cancer cells by retinoic acid." (PMID 25806093, 2015). "The median methylation prevalence of RARβ gene promoter was 47.56% and 17.50% in cancer tissue and autologous controls, respectively." (PMID 24796328, 2014). "In this meta-analysis, the pooled odds ratio of RARβ promoter methylation in cancer tissue was 3.60 (95%CI: 2.46–5.27, p = 0.000) versus autologous controls with random-effect model." (PMID 24796328, 2014). "The pooled odds ratio of RARβ promoter methylation in cancer tissue was 3.60 (95%CI: 2.46–5.27) compared to autologous controls with random-effect model." (PMID 24796328, 2014). "According to previous reports, the anti-cancer potential of RA is mainly mediated by RARβ which increases the expression of the migration-related protein E-cadherin." (PMID 24720764, 2014).